CDKN2A (cyclin dependent kinase inhibitor 2A)
Diseases named in the same sentence as CDKN2A in open-access papers (continued):
Sharing a sentence is not in itself a finding about the gene and the disease.
melanoma (continued). "In melanoma, BRAF (71%) followed by CDKN2A (21%) were reported with the highest number of mutations." (PMID 28371134, 2017). "The effects of UV radiation are well known, and several mutations, such as CDKN2A and BRAF mutations, have been shown to correlate with malignant melanoma." (PMID 27999823, 2016). "In melanoma, different pathways are involved, such as the CDKN2A/CDK4 system and pathways involving the extracellular matrix not found in HCL." (PMID 26857260, 2016). "In vivo experiments showed that when oncogenic alterations of BRAFV600E, Cdkn2a−/−, and Pten−/− were induced in the melanocytes of immunocompetent mice, melanomas were generated in 100% of animals but fewer than 10% of the animals developed metastases." (PMID 27598148, 2016). "The most frequently mutated high-penetrance melanoma susceptibility gene is CDKN2A (cyclin-dependent kinase inhibitor 2A), which encodes tumour suppressors p16 and p14ARF." (PMID 26433962, 2016). "Previous studies have shown that the arginine 24 residue within the CDK4 1-70 amino acid region is essential for CDKN2A-binding, and mutations R24C and R24H of CDK4 were shown to inhibit protein binding with CDKN2A in melanoma." (PMID 27708221, 2016). "Nevertheless, our results in this study show that in melanoma cell lines and primary tumors with focal deletion at the CDKN2A/B locus, the transcription of MTAP-ANRIL fusion gene is a frequent occurrence." (PMID 26909863, 2016). "Second, RAS-mutant melanoma and CRC have markedly different patterns of concomitant genomic alterations, such as CDKN2A loss, which are likely to be associated with sensitivity to CDK4/6 inhibitors." (PMID 27167191, 2016). "In summary, our study highlights the contribution of CDKN2A germline deletion to cancer predisposition in LFS/LFL patients and expands the non-melanoma phenotypic spectrum of cancers associated with germline CDKN2A mutations." (PMID 29263814, 2016). "In this study we fine mapped deletions at the 9p21 locus that harbors CDKN2A/B complex to clone the resultant breakpoints in melanoma cell lines derived from metastasized tumors." (PMID 26909863, 2016). "The tumour suppressor p16INK4a, encoded by the CDKN2A gene, is inactivated by mutation, deletion or promoter methylation in 30–70% of melanomas." (PMID 26201960, 2015). "We performed genetic analysis of CDKN2A, CDK4, BAP1, MC1R, and MITFp.E318K in Danish high-risk melanoma cases and found CDKN2A germline mutations in 11.3% of CM families with three or more affected individuals, including four previously undescribed mutations." (PMID 25803691, 2015). "CDKN2A mutation carriers with [R/R, R/r] MC1R genotypes, had a significantly higher risk of developing melanoma compared to other carriers, and had an OR of 2.25 for developing CM 10 years earlier than carriers with [r/r, R/wt, r/wt, wt/wt] MC1R genotypes." (PMID 25803691, 2015). "In this work, we investigated the methylation pattern of germline CDKN2A and other 10 melanoma-related genes in leukocytes of melanoma patients (familial and sporadic cases), relating these findings to melanoma occurrence and clinical characteristics." (PMID 26106605, 2015). "The melanoma patients exhibited low methylation levels for CDKN2A, similar to the pattern already reported for healthy individuals." (PMID 26106605, 2015). "The quantitative bisulfite pyrosequencing of CDKN2A promoter was investigated to determine if any of the melanoma patients exhibited inactivation of this gene by hypermethylation." (PMID 26106605, 2015).
melanoma (continued). "We also investigated p16 mRNA and protein levels from the endogenous CDKN2A locus using a melanoma-derived cell line that retains p16 expression, using polysomal profiling or Western blot." (PMID 26498684, 2015). "In conclusion, we have identified baseline expression signatures in skin cells carrying germline CDKN2A mutations and RHC MC1R variants which are maintained in skin tumors (melanoma and squamous cell carcinomas)." (PMID 24742402, 2014). "Germline high-penetrance mutations are found in 10% of melanoma prone families and somatic CDKN2A alterations are also recurrent events in primary melanomas and melanoma cell lines." (PMID 24742402, 2014). "There are only limited data available on the prevalence of CDKN2A and CDK4 mutations outside the context of familial melanoma." (PMID 25780468, 2014). "For members of families with multiple cases of melanoma, the presence of relatives with multiple primary melanoma (MPM), pancreatic cancer, and early age at onset predict the presence of germline CDKN2A mutations." (PMID 25780468, 2014). "In our study, the presence of multiple primary melanomas was a predictive factor of being a familial case, and the strongest predictive factor of being a CDKN2A carrier, even after multivariate analysis." (PMID 25893138, 2014). "Melanoma cells harvested directly from an HGF-transgenic/CDKN2A-knockout FVB/N mouse were transduced with the ffLuc-eGFP gene ex vivo, and transplanted subcutaneously into syngeneic FVB/N mice." (PMID 25369133, 2014). "Significantly mutated gene analysis using 13 WGS cases and 15 additional paired extension cases identified known melanoma genes such as BRAF, NRAS, and CDKN2A, as well as a novel gene EPHA3, previously implicated in other cancer types." (PMID 25393105, 2014). "Inherited mutations in the p16/CDKN2A gene cause the familial atypical multiple mole melanoma syndrome, with increased risk for developing PDAC and melanoma." (PMID 25250326, 2014). "Mutations or epigenetic silencing of cyclin-dependent kinase inhibitor 2A (CDKN2A or p16) are common genetic abnormality in patients with family history of melanoma." (PMID 23691346, 2013). "In a small group of patients, inherited mutations of the P16INK4A/CDKN2A gene cause familial atypical multiple mole melanoma (FAMM) syndrome, which is associated with an increased risk of developing melanoma and PDAC." (PMID 24084722, 2013). "Cyclin-dependent kinase inhibitor 2A (CDKN2A) is one of the best known genetic factors in melanoma development and codes for two proteins controlling cell proliferation: p16Ink4A and p14ARF." (PMID 23303275, 2013). "Rare deleterious germinal mutations in the cell cycle regulators CDKN2A and cyclin dependent-kinase 4 (CDK4) have been shown to confer a high cutaneous malignant melanoma risk." (PMID 24416617, 2013). "Distribution of age, gender, CDKN2A, pigmentation phenotype, and sun exposure variables in 53 melanoma-prone families by CMM status." (PMID 23990928, 2013). "Rare alleles of CDKN2A and CDK4 genes have been identified in familial forms of melanoma among patients who have had melanoma." (PMID 24416617, 2013). "Their importance is revealed by the fact that germline and somatic mutations in CDKN2A and CDK4 directly or in their associated signaling pathways are almost invariably found in melanomas." (PMID 24416617, 2013).
melanoma (continued). "Distribution of age, gender, CDKN2A, pigmentation phenotype, and sun exposure variables in 53 melanoma-prone families by telomere length, stratified by CMM status." (PMID 23990928, 2013). "Two high-penetrance susceptibility genes, CDKN2A and CDK4 and one low-penetrance gene, MC1R, are well-defined genetic risk factors for melanoma." (PMID 22978401, 2012). "Homo sapiens cyclin-dependent kinase inhibitor 2A (CDKN2A; melanoma, p16, inhibits CDK4), a major CDK inhibitor, is the product of a tumor-suppressor gene that has been found inactivated in different cancer types." (PMID 22690114, 2012). "Deletions of the CDKN2A locus have been found in up to 50% of melanomas, but inactivation of this locus can also occur through mutations and promoter hypermethylation." (PMID 22339359, 2012). "Germline mutations in CDKN2A and CDK4 have been linked to familial melanoma, however mutations in both of these genes have been infrequently reported in young onset melanoma." (PMID 21915125, 2011). "The second study demonstrated that methylthioadenosine phosphorylase (MTAP), a gene adjacent to CDKN2A, and another locus encompassing PLA2G6 (a member of the phospholipase A2 gene family) both showed an association with melanoma risk." (PMID 21203498, 2010). "Two genes have been discovered in melanoma families: CDKN2A (p16) on chromosome 9p21 and CDK4 on chromosome 12." (PMID 20936153, 2010). "Germline mutations in two genes, CDKN2A and (rarely) CDK4, have been shown to cause inherited melanoma susceptibility with high penetrance, and a third such locus has recently been identified on chromosome 1p22." (PMID 20978504, 2010). "The presence of ulceration is an important prognostic factor for melanoma even in stage III or metastatic disease and, therefore, we also assessed the associations between CDKN2A deletion and BRAF/NRAS mutation and ulceration." (PMID 20140953, 2010). "This is consistent with previous studies which have shown that deletion at CDKN2A appears to be the major mechanism of CDKN2A inactivation in primary melanomas." (PMID 20140953, 2010). "Melanoma families have been identified worldwide, but joint efforts have only revealed major melanoma-associated gene mutations in less than halve of the families, mostly CDKN2A mutations, involving two cell cycle controlling proteins called p16 and p14ARF." (PMID 24281082, 2010). "The Cyclin-Dependent Kinase Inhibitor 2A (CDKN2A, also called Multi Tumor-Suppressor MTS1) is the major gene involved in melanoma pathogenesis and predisposition." (PMID 19828018, 2009). "Data obtained from genetic and molecular studies over the past few years have indicated that the CDKN2A locus as the principal and rate-limiting target of UV radiation in melanoma formation." (PMID 19828018, 2009). "Inactivation of CDKN2A by genetic and epigenetic changes has been described in melanoma, squamous cell carcinoma, breast cancer and Hodgkin disease." (PMID 18628759, 2008). "The CDKN2A gene is the major high-risk CMM susceptibility gene identified to date, as germline mutations in this gene have been found in about 20–40% of melanoma-prone families worldwide." (PMID 18612309, 2008). "The patient carrying this novel deletion of CDKN2A presented with dysplastic nevus syndrome and developed five primary melanomas between 45 and 51 years of age." (PMID 18612309, 2008).
melanoma (continued). "The purpose of this study was to assess the contribution of large rearrangements in CDKN2A to the disease in melanoma-prone families using multiplex ligation-dependent probe amplification." (PMID 18612309, 2008). "A large duplication of the CDKN2A/CDKN2B loci has also been reported in a melanoma patient from a Swedish family, but the clinical significance of this variant is not evident." (PMID 18612309, 2008). "A deletion involving CDKN2A exon1α, 2, and 3 and a deletion removing exon 1α and half of exon 2 were described in two melanoma-prone kindreds, originated from UK and from Norway, respectively." (PMID 18612309, 2008). "A number of studies have suggested mutations of CDKN2A and BRCA2 as possible determinants of the higher incidence of melanoma among breast cancer patients." (PMID 17024122, 2006). "Segregation analysis of two melanoma-NST French families showed hemizygous germline deletion that ablated CDKN2A/ARF gene." (PMID 15928671, 2005). "Analysis of 11 families with two or more cases of glioma revealed a hemizygous germline deletion in CDKN2A in one family with both glioma and melanoma." (PMID 15928671, 2005). "Among families with melanoma-NST association, the loss of function of CDKN2A/ARF can be a predisposing factor." (PMID 15928671, 2005). "One melanoma tumor exhibited two heterozygous alterations in the CDKN2A exon 1 one of which was novel (stop codon, and missense mutation)." (PMID 15819981, 2005). "The purpose of our present study was to examine the possible regulatory role of ID1 and ETS transcription factors in melanoma progression, especially since they are known to influence both the CDKN2A/p16 pathway and angiogenesis regulation." (PMID 16189525, 2005). "These melanoma-private mutations occurred in genes linked to chromatin regulation (ARID1A and ARID2), cell growth (e.g., PIK3CA), cell adhesion (e.g., EPHA2), splicing (SF3B1), angiogenesis (PTPRB), and classic tumor suppressors (NOTCH3, CDKN2A, and PTEN)." (PMID 41516405, 2026). "In contrast, substantial loss or complete absence of p16 expression is frequently encountered in malignant melanoma, where it represents a surrogate marker of CDKN2A inactivation, typically due to homozygous deletion, mutation, or promoter hypermethylation." (PMID 41596618, 2026). "While the CDKN2A locus was confirmed as the primary target of allelic loss, a second recurrent deletion was detected at the D9S171 marker, suggesting the existence of an additional melanoma susceptibility gene within the 9p21 region." (PMID 41596618, 2026). "The most common molecular aberration after loss of 3p21 was heterozygous loss of the CDKN2A locus, which, unlike homozygous loss, has not been associated with melanoma." (PMID 39976080, 2025). "This included the melanoma driver mutations NRAS Q61K/R, BRAF V600E, CDKN2A P114L, and HRAS G13." (PMID 40075679, 2025). "The most represented mutations depend on hereditary or sporadic origin, although some mutations such as that involving cyclin-dependent kinase inhibitor 2A (CDKN2A), a gene that encodes a 156 amino acid, 16 kD cell-cycle inhibitor protein, is common in familial and sporadic melanomas." (PMID 40868208, 2025). "In melanoma cells, TBX2 recruits HDAC1 to the p21 promoter, silencing its expression and enabling continued proliferation—even in the absence of CDKN2A, a well-known tumor suppressor frequently mutated in melanoma." (PMID 40723431, 2025).
melanoma (continued). "Among melanoma‐prone families, wild‐type for CDKN2A and CDK4, some have pathogenic variants in genes not usually linked to melanoma." (PMID 40072281, 2025). "Additionally, this cell line expresses BRAFV600E, which activates the MAPK pathway, and expresses AKT1E17K in the context of Cdkn2a and Pten loss, resulting in activation of the PI3K/AKT signaling pathway, which is a common occurrence in human melanoma." (PMID 40944916, 2025). "Cyclin-dependent kinase inhibitor 2A [CDKN2A] gene and cyclin-dependent kinase 4 (CDK4) gene germline mutations, among other less commonly known mutations, are frequently identified genetic abnormalities in familial melanomas." (PMID 41463545, 2025). "Finally, a PV in CDKN2A emerged from MGPT in a BC patient with a positive family history of melanoma who also carried an additional heterozygous PV in MUTYH." (PMID 40361347, 2025). "The index cases were selected based on familial history of melanoma and/or multiple primary melanomas, along with previous negative tests for pathogenic CDKN2A variants." (PMID 40072281, 2025). "At the molecular level, melanoma pathogenesis is driven by genetic alterations in pathways that regulate proliferation, differentiation and apoptosis, with recurrent mutations in genes such as BRAF, NRAS, NF1, KIT, TERT, and CDKN2A." (PMID 41011113, 2025). "For instance, CDKN2A, a cell cycle regulator known for its role in high-grade gliomas and melanoma, has not been implicated in VS, marking it as a potentially novel biomarker." (PMID 41231782, 2025). "In the context of hereditary cancer, CDKN2A is known as the primary high-risk predisposition gene for familial cutaneous melanoma (OMIM #155601), with inactivating germline variants found in approximately 10%–40% of melanoma-prone families." (PMID 40917369, 2025). "Regarding tumor suppressors, CDKN2A, the CDK4/6 inhibitor, which is deleted or mutated in 40% of melanomas, and the PI3K/AKT pathway inhibitor, which exhibits characteristic loss of function in 20–30% of melanomas, were considered." (PMID 40647405, 2025). "The aim of the present work was to identify potential pathogenic germline genetic variants in melanoma‐prone families without any detected pathogenic alterations in CDKN2A or CDK4." (PMID 40072281, 2025). "The association of CDKN2A ALT with reduced benefit from ICI therapy is found in urothelial carcinoma (UC), not in five other cancers: esophagogastric cancer, head and neck cancer, NSCLC, renal cell carcinomas, and melanoma." (PMID 38822443, 2024). "Importantly, miR-876 expression was profoundly downregulated in both melanoma tissues and cell lines, with evidence of downregulated CDKN2A expression also being present in the same panel of melanoma cell lines." (PMID 39138582, 2024). "However, we did not observe any associations between the most frequent somatic mutations (BRAF, CDKN2A, PTEN, NRAS) and Treg infiltration in AYA melanoma." (PMID 38589406, 2024).